RPL13AP7 (ribosomal protein L13a pseudogene 7)
Gene: Transcribed processed pseudogene on chromosome 21 (25,361,821 to 25,362,431, forward strand). Ensembl gene ENSG00000213885.
Diseases named in the same sentence as RPL13AP7 in open-access papers:
RPL13AP7 is named in the same sentence as 1 disease in open-access papers, as found by Europe PMC text mining. Sharing a sentence is not in itself a finding about the gene and the disease. The quoted sentences say what the papers report.
Sepsis (1 paper, 2017). Sepsis is defined as life-threatening organ dysfunction caused by a dysregulated host response to infection. "Thus, we identified the lncRNAs RP11-159C21.4, RP11-179H18.5, RP11-302F12.1, RP3-486D24.1, and RPL13AP7 as candidates to be further investigated as biomarkers for sepsis." (PMID 29657277, 2017).